MRPL45 (mitochondrial ribosomal protein L45)
Description:
Component of the mitochondrial large ribosomal subunit (mt-LSU). Within the mitochondrial ribosomes, required to direct the nascent polypeptide toward the tunnel exit and position the exit at a distance from the membrane surface.
Synonyms: L45mt; MRP-L45; MGC11321; Mba1; mL45
Gene: Protein-coding gene on chromosome 17 (38,297,023 to 38,323,218, forward strand). Ensembl gene ENSG00000278845.
Subcellular location: Mitochondrion
Subcellular location (Human Protein Atlas): Mitochondria
Genetic constraint (gnomAD): Loss-of-function variants: 20 observed, 36 expected, observed/expected ratio (o/e) 0.56, 90% interval 0.39 to 0.81. The upper end of that interval is the gene's LOEUF score, 0.81, which puts it in group 3 of 6, group 1 being the genes least tolerant of losing a copy. Missense variants: 301 observed, 363.24 expected, observed/expected ratio (o/e) 0.83, 90% interval 0.75 to 0.91. Synonymous variants: 95 observed, 119.26 expected, observed/expected ratio (o/e) 0.8, 90% interval 0.67 to 0.94.
Homologues: Orthologues: macaque MRPL45 (95% identical), chimpanzee MRPL45 (89% identical), pig MRPL45 (84% identical), dog MRPL45 (81% identical), mouse Mrpl45 (80% identical), rabbit MRPL45 (79% identical), guinea pig MRPL45 (77% identical), rat Mrpl45 (73% identical), zebrafish mrpl45 (54% identical), tropical clawed frog mrpl45 (53% identical), Drosophila melanogaster mRpL45 (39% identical), Caenorhabditis elegans mrpl-45 (34% identical).
Diseases named in the same sentence as MRPL45 in open-access papers:
MRPL45 is named in the same sentence as 8 diseases in open-access papers, as found by Europe PMC text mining. Sharing a sentence is not in itself a finding about the gene and the disease. The quoted sentences say what the papers report.
cancer (1 paper, 2024). A tumor composed of atypical neoplastic, often pleomorphic cells that invade other tissues. "Transcriptomes of cancer cell line encyclopedia revealed that SUCLG1 expression showed a significantly positive correlation with MRPL45." (PMID 38649537, 2024).
tumor (1 paper, 2025). "In summary, metformin may suppress tumor growth by inhibiting PLC via GCDH/MRPL45‐mediated fatty acid oxidation and activating the cGMP‐PKG pathway, although this putative mechanism remains to be validated by further studies." (PMID 41189590, 2025).
MRPL45 also shares sentences with these, for which no sentence is quoted: breast carcinoma (1 paper); lung carcinoma (1); medulloblastoma (1); ovarian carcinoma (1); prostate carcinoma (1); renal cell cancer (1).